TMEM176A (transmembrane protein 176A)
Diseases named in the same sentence as TMEM176A in open-access papers (continued):
Sharing a sentence is not in itself a finding about the gene and the disease.
tumor (17 papers, 2017 to 2025). "Methylation of the TMEM176A promoter was significantly associated with tumor cell differentiation (P < 0.05) and was an independent prognostic factor for poor 3-year overall survival (OS, P < 0.05)." (PMID 30400968, 2018). "Methylation of TMEM176A is associated with tumor cell differentiation and poor 3-year overall survival (OS)." (PMID 30400968, 2018). "Under univariate analysis, TMEM176A methylation (hazard ratio= 2.25, p< 0.01) and tumor differentiation (hazard ratio= 1.841, p< 0.01) were risk factors for poor 5-years OS." (PMID 29050260, 2017). "Methylation of TMEM176A was significantly associated with tumor differentiation and poor 5-years OS." (PMID 29050260, 2017). "Under multivariate analysis, the risk factors of poor OS were TMEM176A methylation (hazard ratio= 2.237, p<0.01) and tumor differentiation (hazard ratio= 1.894, p<0.01)." (PMID 29050260, 2017). "Human TMEM176A was first identified from a screen of tumor-associated antigens in HCC." (PMID 30400968, 2018). "In addition, methylation of TMEM176A was associated with tumor differentiation and was an independent prognostic factor for poor 3-year OS." (PMID 30400968, 2018). "To understand if TMEM176A was also important for tumor growth, we silenced TMEM176A using two shRNA constructs (TMEM176Ash1 and TMEM176Ash2) in MDA-MB-231 cells." (PMID 34943938, 2021). "The tumor volume was reduced significantly in TMEM176A re-expressed LM3 cell xenograft mice (t test, P < 0.001)." (PMID 30400968, 2018). "The tumor weight was 0.67 ± 0.12 g vs. 0.19 ± 0.04 g in TMEM176A unexpressed and re-expressed LM3 cell xenograft mice, respectively." (PMID 30400968, 2018). "The tumor weight was reduced significantly in TMEM176A re-expressed LM3 cells xenograft mice (t test, P < 0.001)." (PMID 30400968, 2018). "The tumor volume was 1090.58 ± 62.48 vs. 614.43 ± 52.7 mm3 in TMEM176A unexpressed and re-expressed LM3 cell xenografts, respectively." (PMID 30400968, 2018). "The tumor volumes were 257.77 ± 164.65 mm3 and 129.72 ± 45.22 mm3 in TMEM176A unexpressed and re-expressed KYSE410 cell xenografts, respectively." (PMID 29050260, 2017). "The tumor weights were 0.27 ± 0.07g and 0.12 ± 0.03g in TMEM176A unexpressed and re-expressed KYSE410 cell xenografts, respectively." (PMID 29050260, 2017). "The tumor volume was significantly smaller in TMEM176A re-expression KYSE410 cell xenografts compared to TMEM176A unexpressed KYSE410 cell xenografts (P<0.05)." (PMID 29050260, 2017). "Furthermore, TMEM176A inhibited cell growth both in vitro and in vivo with a decrease in tumor volume when TMEM176A was re-expressed." (PMID 30574087, 2018). "Previous research demonstrated TMEM176A may participate in tumor invasion through the EMT process." (PMID 37265785, 2023). "Two recent studies also showed that TMEM176A could act as tumor suppressor." (PMID 30574087, 2018). "Single-cell and spatial transcriptomics localized TMEM176A to fibroblasts and SRI to the tumor epithelium." (PMID 41228276, 2025). "Spatial transcriptomics localized TMEM176A to fibroblasts and SRI to tumor epithelium, and in vitro SRI knockdown inhibited tumor cell growth, migration and invasion." (PMID 41228276, 2025). "Additional outcomes revealed the expression of TMEM176A and TMEM176B was almost parallel followed by pseudo-time, and evidently elevated in tumor-infiltrating Mac2 and DC1 (logFC>1, P<0.01)." (PMID 37265785, 2023). "Some of TMEM proteins act as tumor suppressors such as TMEM7, TMEM25, TMEM97, and TMEM176A; while a large number of them act as oncogenes such as TMEM14A and TMEM158." (PMID 37335919, 2023). "According to the tumor grades, in TCGA database, compared with WHO II and III, the transcription levels of MS4A4A, MS4A4E, MS4A6A, MS4A7, TMEM176A, and TMEM176B were the highest in WHO IV." (PMID 35734424, 2022). "Emerging evidence has demonstrated that the TMEM family, including TMEM176A and TMEM45B, is involved in tumor progression, metastasis, and chemo-resistance." (PMID 35713314, 2022).
tumor (continued). "Thus, TMEM176A may serve as a tumor suppressor in human HCC." (PMID 30400968, 2018). "However, the role of FGD3, TMEM176A, CD1B and MATK in anti‐tumor immunity remains unclear." (PMID 36814908, 2023). "In our study, we found up-regulated expression of TMEM176A and TMEM176B both in malignant cells and myeloid cells, which might negatively affect the differentiation of DC cells leading to the potential imbalance of antigen presentation and promoting tumor immune escape." (PMID 37265785, 2023).
cancer (15 papers, 2017 to 2026). A tumor composed of atypical neoplastic, often pleomorphic cells that invade other tissues. "TMEM176A is located in human chromosome 7q36.1, a region where there is a frequent loss of heterozygosity in human cancer." (PMID 30400968, 2018). "Through literature reviews, it has been observed that TMEM176A assumes diverse roles across various types of cancers." (PMID 39001509, 2024). "While investigating the prognostic potential of cMo IFN in cancer patients, we observed significant overexpression of TMEM176A and TMEM176B genes in cMo IFN from responders, though both genes were differentially expressed even before treatment." (PMID 36263038, 2022). "The Cancer Genome Atlas (TCGA) database was employed to further validate that the expression of TMEM176A is regulated by promoter region methylation." (PMID 30400968, 2018). "TMEM176A was expressed in adjacent tissue samples and its expression was reduced in primary cancer samples." (PMID 29050260, 2017). "Recently, the epigenetic regulation of TMEM176A has been uncovered in cancer." (PMID 36814908, 2023). "TMEM176A and TMEM176B are unique members of the MS4A family with distinct expression characteristics, and recent studies have improved our understanding of their structures, distribution patterns, biological functions, and associations with various clinical diseases, including cancer." (PMID 39717774, 2024). "The function of human transmembrane protein 176A (TMEM176A) in cancer remains unclear." (PMID 29050260, 2017). "Moreover, TMEM176A and TMEM176B have been demonstrated to have a role in the regulation of cancer pathology." (PMID 39001509, 2024). "Although human TMEM176A was identified in 2002, no direct evidence has been established indicating that TMEM176A is a cancer related protein." (PMID 29050260, 2017). "Evidence on the functional relevance of TMEM176A in cancer development is also lacking." (PMID 29050260, 2017).
immune disorders (1 paper, 2016). "High expression of Tmem176a and b in RORγt+ cells suggests that these homologues play a role in immune disorders involving protective or pathogenic actions of these cells." (PMID 27009467, 2016).
TMEM176A also shares sentences with these, for which no sentence is quoted: esophageal squamous cell carcinoma (2 papers); lymphoma (2); melanoma (2); Behcet’s syndrome (1); colitis (1); dermatitis (1); experimental autoimmune encephalomyelitis (1); fibrosarcoma (1); infection (1); knee osteoarthritis (1); liver cirrhosis (1); prostate carcinoma (1); psoriasis (1); skin cancer (1); skin inflammation (1).